S100B (S100 calcium binding protein B)
Diseases named in the same sentence as S100B in open-access papers (continued):
Sharing a sentence is not in itself a finding about the gene and the disease.
epilepsy (continued). "Although there are many studies on S100B, the mechanism by which S100B leads to epilepsy is unclear." (PMID 33959658, 2021). "Two recent meta-analyses also provided evidence for the increase of serum S100B levels in patients with epilepsy." (PMID 33959658, 2021). "In 1070 days median follow-up for 90 patients on mechanical thrombectomy treatment, Eriksson proved that multiple serology indicators, including S100B in patients with poststroke epilepsy, are higher than normal." (PMID 33959658, 2021). "Recent meta-analyses of several cohorts provide a multitude of evidence that support the elevation of S100B protein level in epilepsy patients." (PMID 33959658, 2021). "Increase in the serum level of S100-B in patients with epilepsy and infants suffering from epileptic seizures has revealed the high potency of this protein for clinical diagnosis of epilepsy." (PMID 33244522, 2020). "For instance, since steroid-induced decreases in S100b levels have been shown to reduce inflammation in the hippocampus in a rat model of epilepsy, the significant decrease in expression of S100b at one year post-TBI would protect against inflammation." (PMID 30943276, 2019). "Conclusion and relevance: the results of this meta-analysis provide evidence for a significant increase in serum S100B levels in patients with epilepsy." (PMID 31156363, 2019). "Main outcomes and measures: Peripheral blood levels of S100B in patients with epilepsy compared with controls." (PMID 31156363, 2019). "Serum S100B is the most worthwhile biomarker of epilepsy, which is helpful for the clinical diagnosis and prognosis of epilepsy." (PMID 31156363, 2019). "Here, we reported that astrocytes and S100B proteins significantly increased during KA-induced epilepsy." (PMID 21837247, 2012). "Several studies have shown that S100B proteins are involved in the development of epilepsy, but the relationship between UR and S100B is unclear." (PMID 21837247, 2012). "Furthermore, different investigations have linked elevated serum and brain concentrations of S100B with the most severe cases of epilepsy." (PMID 40076950, 2025). "Modulators of Ca2+ exchangers, blockers of aberrant gliotransmission, or interventions aimed at restoring buffering proteins like S100β could provide new treatment strategies for epilepsy, neurodegeneration, and neurodevelopmental disorders." (PMID 41227353, 2025). "Chronically elevated MMP-9 and S100B in epilepsy patients above the levels observed in age-matched controls might therefore indicate neurodegenerative processes (such as in mesial temporal sclerosis) or epileptic discharge activity." (PMID 40076533, 2025). "Blood neurofilament light, glial fibrillary acidic protein, total tau, S100 calcium-binding protein B and neuron-specific enolase concentrations were measured in 444 patients (aged ≥ 18 years) with epilepsy participating in a prospective regional Biobank study in Västra Götaland (Sweden)." (PMID 40114782, 2025). "Likewise, levels of S100B secreted from hippocampal slices from a pilocarpine-induced model of epilepsy were reduced by dexamethasone treatment." (PMID 37298554, 2023). "The molecules whose levels are chronically elevated in serum of patients with epilepsy (MMP-2, MMP-9, S100B, TIMP-1, TIMP-2) might be considered diagnostic biomarkers of epilepsy." (PMID 36766708, 2023). "Several studies have indicated that elevated levels of S100β in the cerebrospinal fluid and temporal lobe of epilepsy patients may be attributed to increased production or release by dysfunctional astrocytes." (PMID 37833937, 2023). "Serum S100B levels have been found to be significantly elevated in patients with epilepsy or infants with epileptic seizures, and S100B has been proposed by many authors as a clinically relevant peripheral biomarker in epilepsy." (PMID 38203674, 2023).
epilepsy (continued). "Indeed, the administration of arundic acid (an S100B inhibitor) to murine models of epilepsy reduced neuroinflammation and improved astrocytic function after status epilepticus." (PMID 36771418, 2023). "Here, we studied the correspondence of the expression of BDNF, NSE, VILIP-1, and S100B in the blood (serum and PBMCs) with the in vivo content in the hippocampuses of patients with drug-resistant epilepsy using biosamples obtained during neurosurgical operations." (PMID 38203674, 2023). "In chronic epilepsy, several studies have reported increased serum levels of S100B in epilepsy patients compared to healthy controls, and its concentrations may reflect epilepsy severity, suggesting its potential prognostic value." (PMID 37569895, 2023). "Yet, in patients with epilepsy, the serum S100B level was higher in men." (PMID 36766708, 2023). "A set of molecules associated with BBB permeability (MMP-2, MMP-9, S100B), restoration (TIMP-1, TIMP-2, TSP-2), neuroinflammation (CCL-2), and endothelial activation (ICAM-1, P-sel) that are affected in epilepsy and can be measured in blood was selected in this study." (PMID 36766708, 2023). "NfL, tau, NSE and S100B have repeatedly been reported useful as circulating biomarkers of cerebral injury in other neurological disorders such as neurodegenerative disease, traumatic brain injury and epilepsy." (PMID 35269411, 2022). "S100B level < 1.364 (P = 0.001) is an independent predictor of poststroke epilepsy." (PMID 33959658, 2021). "Although the inclusion criteria are different, many studies have shown that the serum S100B in epilepsy patients is significantly higher than that in the control group regardless of the aetiology and location of the seizures, and this increases with increased frequency of seizures." (PMID 33959658, 2021). "The search terms included S100B and calcium-binding protein B in combination with epilepsy." (PMID 31156363, 2019). "Results: a fixed-effects meta-analysis of all 18 studies, including 1,057 unique participants, indicated that patients with epilepsy had significantly increased peripheral blood levels of S100B compared to controls (Hedges g = 1.568, 95% CI =1.431-1.706, P < 0.001)." (PMID 31156363, 2019). "In fact, extracellular levels of S100B are elevated in Li-pilocarpine model of epilepsy." (PMID 29506554, 2018). "Interestingly, these time-dependent changes in S100B secretion of the hippocampal slices of SE animals coincide with changes of this protein observed in CSF in the Li-pilocarpine model of epilepsy." (PMID 29506554, 2018). "We also wished to test the hypothesis that in clinical epilepsy S100B surges precede seizures as shown in experimental models." (PMID 24988410, 2014). "Interestingly, levels of brain S100B in epileptic patients are increased compared with controls, and S100B release is increased in a mouse model of epilepsy." (PMID 20827421, 2010). "The increased presence of S100β may potentially have proapoptotic effects, as it has been shown to upregulate nitric oxide (NO) expression, leading to neuronal and glial cell death and potentially participating in the pathogenesis of epilepsy." (PMID 37833937, 2023). "We showed that serum levels of molecules associated with BBB disruption (MMP-2, MMP-9, S100B) and restoration (TIMP-1, TIMP-2) are increased in patients with epilepsy in the interictal period, which might reflect chronic processes taking place at the BBB, even in the absence of seizures." (PMID 36766708, 2023). "Moreover, S100B is related to tumors, mental disorders, epilepsy, and brain injury." (PMID 35989914, 2022). "Transgenic mice overexpressing S100B display altered synaptic plasticity and impaired spatial learning and social behaviors, whereas inactivation of S100B induces chronic astrogliosis, enhances synaptic plasticity and increases the incidents of epilepsy and blood–brain barrier permeability." (PMID 34615523, 2021).
epilepsy (continued). "Aberrations in peripheral blood levels of S100B were hypothesized to be related to epilepsy." (PMID 31156363, 2019). "Importance: Accumulating evidence suggests that serum levels of S100B may play a role in epilepsy." (PMID 31156363, 2019). "Previous studies have demonstrated that tonic–clonic seizures in individuals with epilepsy result in elevated serum concentrations of MMP-9 and S100B." (PMID 40076533, 2025). "When comparing our results to previous studies on epilepsy, the increases in MMP-9 and S100B levels after seizures appear to be higher and more prolonged." (PMID 40076533, 2025). "We explored blood levels of NfL, GFAP, total tau, S100B and NSE in a regional epilepsy cohort, with a focus on DRE." (PMID 40114782, 2025). "For example, in an epilepsy model, Dex administration has been found to improve inflammation, prevent astrogliosis (based on GFAP and S100β expression), and partially reduce astroglial dysfunction." (PMID 39036088, 2024). "Nevertheless, the results of a recent meta-analysis indicate that patients with epilepsy have higher serum levels of S100B, which is in concordance with our results and suggests chronic increase of BBB permeability in patients with epilepsy." (PMID 36766708, 2023). "Elevation of serum level of S100B, which is a well-known biomarker of BBB activation/disruption, suggests that this process is present in patients with epilepsy in the interictal period." (PMID 36766708, 2023). "Serum levels of MMP-9, MMP-2, TIMP-1, TIMP-2, S100B, CCL-2, ICAM-1, P-selectin, and TSP-2 were examined in a group of 49 patients with epilepsy who were seizure-free for a minimum of seven days and measured by ELISA." (PMID 36499038, 2022). "We suggested in our previous studies that UR lowers KA-induced lipid peroxide levels and offers neuroprotection against KA-induced epilepsy by regulating GFAP and S100B." (PMID 28386293, 2017). "S100B appears to be a promising biomarker in epilepsy, as it is not induced by physical activity but does increase following seizures." (PMID 40076533, 2025). "Interestingly, the level of S100β expression in the cortex and white matter was found to be lower in children with DRE compared to adults with epilepsy." (PMID 37833937, 2023). "However, in the hippocampal slices from rats submitted to the Li-pilocarpine model of epilepsy, S100B secretion did not change in high-potassium medium, although the reason for this lack of change in S100B secretion is unclear at the moment, as is the mechanism by which S100B secretion occurs." (PMID 29506554, 2018).
diabetes (33 papers, 2010 to 2025). "Beyond its potential protective role in inflammatory bowel diseases, S100B has been implicated in other chronic disorders, including obesity, type 2 diabetes mellitus (T2DM), and various neurological and neuroinflammatory conditions." (PMID 40723919, 2025). "A preliminary consideration necessarily points out that most of the reported data indicate more of a correlation than a causation between S100B and obesity/diabetes." (PMID 38255850, 2024). "This review tunes the possible role of S100B in pathogenic processes of obesity/diabetes interpreting together recent and less recent data, the latter having been probably disregarded and received inadequate attention in recent times." (PMID 38255850, 2024). "Serum S100B levels were also increased in patients with diabetes – a vascular risk factor – and cognitive decline compared to cognitively intact patients with diabetes." (PMID 35910248, 2022). "Upregulation of RAGE and S100B has previously been linked to the activation of microglia and the induction of Müller cell inflammatory cytokine expression in diabetes." (PMID 30112688, 2018). "Our observation showed that the expression quantity of S100B in diabetic rats induced by STZ was associated with diabetes duration." (PMID 24860604, 2014). "However, consistent research has shown interesting associations between S100B and adipose tissue in the context of obesity, metabolic disorders, and diabetes." (PMID 38255850, 2024). "In the light of consistent research showing some associations between S100B and adipose tissue in the context of obesity, metabolic disorders, and diabetes, this review tunes the possible role of S100B in the pathogenic processes of these disorders, which are known to involve the adipose tissue." (PMID 38255850, 2024). "The reported data suggest a role for adipose S100B in obesity/diabetes processes, thus putatively re-proposing the role played by astrocytic S100B in neuroinflammatory/neurodegenerative processes." (PMID 38255850, 2024). "Another participant in obesity/diabetes (diabesity) processes, putatively involving S100B, is the gut microbiome." (PMID 38255850, 2024). "Hopefully, this review will constitute a stimulation towards studies addressing the putative role of S100B protein in obesity/diabetes processes." (PMID 38255850, 2024). "Eight risk factors (1 kg higher body weight, diabetes, education, hypertension, hypercholesterolemia, pre-operative C-reactive protein (CRP), pre-operative interleukin 6, pre-operative S100b) were detected in a mix of surgery types." (PMID 36836145, 2023). "In any case, with this potential problem in mind, this review will focus on the involvement of S100B in diseases of the nervous system, leaving out extra neural disorders such as obesity, diabetes, and melanoma." (PMID 37298554, 2023). "A study in S100B knock-out (KO) mice showed that these mice are resistant against experimental diabetes induced by streptozotocin, compared to wild-type mice." (PMID 33671490, 2021). "In the present study, the results showed that oxidative stress not only accelerated the pathogenesis of cerebral dysfunction but also significantly increased the ROS levels and S-100B levels in diabetes." (PMID 33273999, 2020). "After adjusting for classical cardiovascular risk factors such as age, gender, body mass index, smoking, hypercholesterolemia, hypertension and diabetes, the association between AMI patients and S100B rs9722 remained significant." (PMID 33796567, 2020). "It has previously been demonstrated that the pattern recognition receptor, RAGE, is upregulated in retinal Müller cells after 3 months of diabetes, together with one of its major ligands, S100B." (PMID 30112688, 2018). "S100B secretion from adipocytes is related to lipolysis, inhibited by insulin, and thus is subject to dysregulation by diabetes and other metabolic diseases." (PMID 29681765, 2018).
diabetes (continued). "We also demonstrated that the expression of S100B protein which was used frequently as EGC marker decreased in 56–63-day diabetes rats." (PMID 24860604, 2014). "RT-PCR studies showed that the change trends of S100B were decreased with the course of diabetes, especially in the TDM (0.19 ± 0.05 versus 0.70 ± 0.09, P < 0.01)." (PMID 24860604, 2014). "The effects of SGES on S100B expression in 7–14-day diabetes rats are little which indicates the other factors such as the fact that ghrelin is involved in S100B." (PMID 24860604, 2014). "In the severe diabetes group, the levels of S100B, NSE, MBP and ET-1 were all significantly higher compared with those in the control group (P<0.01)." (PMID 25371752, 2014). "In the retina, S100B is constitutively expressed by astrocytes and Müller glia although it is upregulated in conditions such as diabetes where it can provoke inflammatory cytokine expression via RAGE-activation of p44/42, p38, JNK and/or p90RSK." (PMID 24586862, 2014). "Additionally, in streptozotocin-induced diabetes, the S100b protein was reported to be elevated by two, yet the mRNA was reduced." (PMID 39063010, 2024). "Indeed, inflammatory processes involving DAMPs, as S100B is considered, are widely regarded to be active in obesity/diabetes." (PMID 38255850, 2024). "We used the univariate logistic regression to analyze the association between sex, age, BMI, history of diabetes, hypertension, SBP, DBP, GCS, affected side, hematoma volume, therapy type, FMA-WH score admission, BMR score admission, CAF, S100B, NfL and poor motor function." (PMID 36068493, 2022). "Collectively, those studies suggested that S100B expression may beneficially modulate cardiac metabolism post-MI in diabetes." (PMID 32211423, 2020). "Interestingly, when these NPPEs are used to prevent diabetes in this animal model, an acceleration of the disease is observed together with an exacerbation in insulitis and an increase in S100-β–specific cytotoxicity in vaccinated animals." (PMID 30817223, 2019). "Immunotherapies employing either whole GFAP or S100-β protect NOD mice from diabetes development." (PMID 30817223, 2019). "When SGES was taken, the increased S100B may be offset by the increased ghrelin concentrations at early stage of diabetes rats." (PMID 24860604, 2014). "Moreover, both adipose and brain tissues increase S100B protein content when exposed to streptozotocin in diabetes or dementia models." (PMID 20672003, 2010). "However, a specific contribution of S100B to paracrine communication in adipose tissue demands further investigation, possibly providing a target for therapeutic intervention in obesity, diabetes and cardiovascular diseases." (PMID 20672003, 2010). "In addition, S100B knockout mice, unable to synthesize S100B, are resistant to diabetes induced by streptozotocin, exhibiting enhanced insulin sensitivity, glucose tolerance, prevention of β cell destruction, and lower urine volume, food, and water intake compared to wild-type mice." (PMID 38255850, 2024). "Furthermore, diabetes produced changes in protein expression, measured by Western blot, with an increase in S100β and a decrease in GFAP production, accompanied by a decrease in cells co-expressing S100β and GFAP in the jejunum mucosa, as observed in cryostat sections." (PMID 34205534, 2021). "In addition, the NSE concentration was significantly higher in the severe diabetes group when compared with the mild diabetes group (P<0.05), while the levels of S100B, MBP and ET-1 exhibited a highly statistically significant difference when comparing the two groups (P<0.01)." (PMID 25371752, 2014). "When the pre-treatment and post-treatment values of patients with DKA were compared with those of the healthy control group, the S100B level, TOL, TAL and OSI were found to be significantly higher in the diabetes group (p<0.001)." (PMID 26316432, 2015).